CCDC27 (coiled-coil domain containing 27)
Synonyms: FLJ32825
Tractability: PROTAC: ubiquitination databases record sites on it.
Gene: Protein-coding gene on chromosome 1 (3,746,460 to 3,771,645, forward strand). Ensembl gene ENSG00000162592.
Subcellular location (Human Protein Atlas): Cytosol; Nucleoplasm
Gene Ontology:
Molecular function: protein binding
Genetic constraint (gnomAD): Loss-of-function variants: 76 observed, 74.56 expected, observed/expected ratio (o/e) 1.02, 90% interval 0.85 to 1.23. The upper end of that interval is the gene's LOEUF score, 1.23, which puts it in group 5 of 6, group 1 being the genes least tolerant of losing a copy. Missense variants: 809 observed, 815.64 expected, observed/expected ratio (o/e) 0.99, 90% interval 0.94 to 1.05. Synonymous variants: 338 observed, 336.14 expected, observed/expected ratio (o/e) 1.01, 90% interval 0.92 to 1.1.
Homologues: Orthologues: chimpanzee CCDC27 (96% identical), macaque CCDC27 (91% identical), dog CCDC27 (52% identical), mouse Ccdc27 (49% identical), rat Ccdc27 (49% identical), tropical clawed frog ccdc27 (25% identical). Paralogues in human: FHAD1 (15% identical).
Diseases named in the same sentence as CCDC27 in open-access papers:
CCDC27 is named in the same sentence as 1 disease in open-access papers, as found by Europe PMC text mining. Sharing a sentence is not in itself a finding about the gene and the disease.
CCDC27 shares sentences with these, for which no sentence is quoted: angiosarcoma (1 paper).